STAT3 (signal transducer and activator of transcription 3)
Diseases named in the same sentence as STAT3 in open-access papers (continued):
Sharing a sentence is not in itself a finding about the gene and the disease.
lymphoma (continued). "Following progression, she was enrolled on protocol treatment with an AKT inhibitor, MK2206, (NCT01258998) with progression of lymphoma after 2 cycles and then received 2 cycles on a STAT3 inhibitor trial (NCT01563302)." (PMID 24395633, 2014). "In lymphomas, the expression and activation of STAT3 have previously been investigated in human lymphoma tissues and cell lines." (PMID 25472725, 2014). "Our findings indicate that STAT3 inhibition in lymphoma patients will impair NK cell-mediated tumor surveillance, which needs to be taken into account when testing STAT3 inhibitors in preclinical or clinical trials." (PMID 24473086, 2014). "SYK is a master regulator of apoptosis controlling the activation of the PI3-K/AKT, NFκB, and STAT3 pathways, three major anti-apoptotic signaling pathways in B-lineage leukemia/lymphoma cells." (PMID 24851191, 2014). "Compared with the germinal center B-cell−like form, activated B-cell−like lymphomas respond much more poorly to current therapies and often exhibit overexpression or overactivation of STAT3." (PMID 24142927, 2013). "Oral administrations of STX-0119 arrested the growth of human lymphoma cells in a SCC-3 subcutaneous xenograft model through inhibition of STAT3 activity." (PMID 24308725, 2013). "AZD9150 (ISIS-STAT3Rx or ISIS 481464), a synthetic ASO against STAT3, underwent phase I evaluation in patients with advanced lymphoma and solid tumors." (PMID 24308725, 2013). "STAT3 is indeed constitutively activated in this lymphoma and its growth seems to be dependent on the STAT3 signaling." (PMID 22412839, 2012). "Inhibition of SYK with a small molecule drug candidate prevented oxidative stress-induced activation of STAT3 and overcame the resistance of human B-lineage leukemia/lymphoma cells to apoptosis." (PMID 23021489, 2012). "STAT3 is constitutively expressed in MM, leukemia, lymphoma, squamous cell carcinoma, and other solid tumors, including cancers of the prostate, breast, head and neck, and nasopharynx." (PMID 22177381, 2011). "Previous studies have reported that STAT3 is constitutively activated in a growing number of tumor-derived cell lines and samples from human cancers, including lymphomas and leukemias." (PMID 22177381, 2011). "LM, LR, and LMR lymphoma cells all exhibited phosphorylation of Stat3 that decreased upon inactivation of MYC and/or K-rasG12D." (PMID 18461184, 2008). "In contrast, Stat3 becomes dephosphorylated in lymphoma cells upon inactivation of MYC and/or K-rasG12D." (PMID 18461184, 2008). "In addition, elevated levels of C5a in co-culture with M2 macrophages lead to increased lymphoma cell proliferation via Stat3 activation." (PMID 41030738, 2025). "Additionally, mutations in nRTKs contribute to the expression of the oncoprotein BCR–ABL, which has been associated with the development of hematological malignancies, including leukemia, lymphoma, and myeloma, through the STAT3 signaling pathway." (PMID 40166646, 2025). "STAT3 inhibition imparts sensitivity of lymphoma cells to chemotherapeutic drugs, and activation of Sestrins might be a potential mechanism to improve the outcome of anticancer therapies." (PMID 39985075, 2025). "Exploring the pathophysiology between C5a, Stat3, and M2 macrophages may lead to a new breakthrough in the treatment of lymphoma." (PMID 41030738, 2025). "Lymphoma cell activation by C5a was suppressed when Stat3 was downregulated." (PMID 41030738, 2025). "The IL-27/STAT3 signaling axis also induces the expression of immune checkpoint molecules including programmed death-1 (PD-1) and programmed death-2 (PD-2) in macrophages in lymphoma." (PMID 38245798, 2024). "Whether lymphoma cells activate the STAT3/STAT6 signaling pathway in bone marrow-derived macrophages was investigated." (PMID 38261741, 2024). "Consequently, targeting JAK/STAT3 signaling can inhibit tumor growth and enhance antitumor immune responses, making STAT3 a promising therapeutic target in lymphoma." (PMID 38817669, 2024).
lymphoma (continued). "Based on the outcomes of clinical trials, several STAT-3 inhibitors were well tolerated, and they may increase the overall survival of cancer patients, including lymphoma cases." (PMID 37175040, 2023). "To examine whether the inhibition of STAT3 induces lymphoma cell apoptosis, we treated the A20, SU-DHL-2, and OCI-Ly3 cells with different conjugates." (PMID 37686472, 2023). "The constitutive activation of STAT3 correlates with a worse prognosis in human lymphoma." (PMID 37686472, 2023). "With the use of an A20 lymphoma model, we showed that this conjugate could specifically inhibit the overexpressed STAT3 activity in lymphoma cells." (PMID 37686472, 2023). "STAT3 functions mainly as a transcription factor and has been shown to be involved in tumor cell proliferation, survival, and invasion in many types of human malignant tumors, including lymphoma." (PMID 37686472, 2023). "Collectively, these studies suggest that STAT3 is a promising target that could be used for lymphoma therapy." (PMID 37686472, 2023). "In addition, in the JAK–STAT pathway, we found the GG genotype of STAT3 rs744166 compared with AA and the T allele of STAT5B rs6503691 compared with C were significantly associated with lymphoma susceptibility." (PMID 37329186, 2023). "The findings of this study suggest that the concomitant inhibition of NFE2L2 and STAT3 may be considered a therapeutic option for the treatment of this lymphoma that poorly responds to chemotherapies." (PMID 37511362, 2023). "Interestingly, the knockdown of STAT3 in A20 lymphoma also leads to a reduced IL-6 production in tumor-bearing mice." (PMID 37686472, 2023). "Recent studies have shown the significant involvement of STAT3 expression in lymphoma development." (PMID 37686472, 2023). "Besides, WP1066, a STAT3 inhibitor, exhibited anti-cancer effects in multiple tumors, including lymphoma, and we found WP1066 enhanced the inhibitory effects of AT56 on DLBCL progression." (PMID 34743203, 2022). "The gain of 19p, the region where a Janus kinase is encoded, may help to clarify the pathogenesis of this lymphoma, due to the involvement of this protein in the phosphorylation of STAT1 and STAT3." (PMID 35406421, 2022). "Similarly, inhibition of HDAC3 in lymphoma cells resulted in nuclear export of STAT3 to the cytoplasm, thus hindering STAT3 function as a transcriptional factor." (PMID 36341403, 2022). "Drugs targeting STAT3 may represent a promising therapeutic option against this cancer, even if several other oncogenic pathways contribute to driving lymphoma cell survival, including PI3K/AKT/mTOR, NFkB, ERK1/2 and mevalonate." (PMID 35743211, 2022). "STAT5B and STAT3 mutations are virtually exclusive in occurrence, whereas STAT5B and PIK3CD mutations potentially complement each other in creating cooperativity between PI3K and JAK-STAT signaling in maintaining proliferation pathways in HSTL lymphoma cells." (PMID 35330161, 2022). "However, JAK1 and JAK2, which are upstream of STAT3, have been mainly demonstrated to play a role in blood system diseases such as myelofibrosis and lymphoma." (PMID 35382859, 2022). "Finally, they demonstrated that the HDAC inhibitor panobinostat (LBH589, used in clinical trials for lymphoma and myeloma) was able to increase the acetylation level of endogenous STAT3 in a dose-dependent manner." (PMID 34440160, 2021). "Therefore, we focused on STAT3 as a potential downstream mediator of IL-6 action in Eμ-myc lymphomas." (PMID 33651821, 2021). "For three of these, the transplant indication was lymphoma, and thus, although the STAT3-HIES was reported as cured, their transplant indication and management could be considered separately." (PMID 33523338, 2021).
lymphoma (continued). "Increased eosinophils, particularly in the skin, have been associated with activation of signal transducer and activator of transcription 3 (STAT3) in CTCL T cells, and additional Janus kinase (JAK)-STAT dysfunction is frequent in CTCL, other T-cell leukemia/lymphomas, and many BIDs." (PMID 32872487, 2020). "DOK-1 usually decreases both JAK-2 and STAT-3/5 phosphorylation in lymphoma cells." (PMID 33333886, 2020). "In addition, STAT3 and STAT5 proteins were shown to contain activating mutations in some rare but aggressive leukemias/lymphomas." (PMID 31963765, 2020). "On the other hand, while stimulating DCs, IL15 inactivated STAT3 in lymphoma cells resulting in TRAIL resistance that could be neutralized by combined treatment with the STAT3 inhibitor Cucurbitacin I leading to an overall effective therapeutic response." (PMID 31333662, 2019). "One explanation for this weak association might be that in addition to EBV other oncogenic factors operating in lymphoma cells influence STAT3-signaling and HLX expression as well." (PMID 31141539, 2019). "Constitutive STAT3 phosphorylation is a common feature in many lymphomas." (PMID 31684088, 2019). "However, our data show that survival of lymphoma cells with activated STAT3/5, MAPK, and NF-κB is maintained." (PMID 31601188, 2019). "Mutated STAT3 is mainly associated with large granular lymphocytic T-cell leukemia, whereas mutated STAT5B is associated with T-cell prolymphocytic leukemia, T-cell acute lymphoblastic leukemia and γδ T-cell-derived lymphomas." (PMID 31817042, 2019). "A lymphoma study reported that IL-27-induced upregulation of PD-L1 in macrophages could be mitigated by STAT3 inhibition, indicating that IL-27 may regulate PD-L1 expression in macrophages via STAT3." (PMID 31781673, 2019). "Here we hypothesize, that Gln metabolism is important for lymphoma proliferation and regulated by a combination of intracellular signaling pathways such as STAT3 and NF-κB, either activated by factors of the microenvironment or intrinsic genetic lesions." (PMID 29666362, 2018). "Activated STAT3 plays an established role in cancer cell survival, and suppressed levels of phosphorylated STAT3 have shown to correlate with better patient survival in lymphoma." (PMID 30446007, 2018). "To validate our findings from cell lines engineered to overexpress STAT3, we tested 7 different NK cell leukemia/lymphoma cell lines with either WT STAT3 (KAI3, NK-92, KHYG-1 and NKL), or naturally occurring STAT3 mutations (YT and NK-YS, Y640F mutation; SNK6, D661V mutation)." (PMID 29228628, 2017). "Top hits were further validated with additional models including STAT3-mutated natural killer (NK)-cell leukemia/lymphoma cell lines and primary large granular lymphocytic (LGL) leukemia cells to assess their ability to inhibit STAT3 phosphorylation and STAT3 dependent cell viability." (PMID 29228628, 2017). "It has been shown that STAT3 increases the content of DNMT1 in malignant T-lymphoma cells." (PMID 28528402, 2017). "In a pilot experiment, over-expression of any of the variants with the GFP retroviral vector on top of endogenous proteins was toxic to the lymphoma cells (loss of 30–50% of GFP+ cells from culture), which suggests that maintaining of a natural ratio of STAT3 variants is critical for cell fitness." (PMID 26727576, 2016). "Moreover, STAT3 has been reported to regulate neutrophil granulogenesis and to induce several kinds of leukemia and lymphoma." (PMID 27658964, 2016).
lymphoma (continued). "STX-0119, a small-molecule inhibitor of STAT3 dimerization, discovered by virtual screening, was able to suppress the growth of SCC3 cells (human lymphoma cell line with highly activated STAT3), through apoptosis and down-regulation of STAT3 targets such as c-myc, cyclin D1, survivin and Bcl-xL." (PMID 27166190, 2016). "STAT3 activation depends on the production of cytokines such as IL-6 produced by the tumor itself or encoded by KSHV, whose infection plays a pivotal role in the pathogenesis of this lymphoma." (PMID 26338963, 2015). "Although JAK1/STAT3 mutants are oncogenic, they require lymphokine engagement (i.e. IL-6, IL-23) and JAK activation, whose inhibition (Ruxolitinib, HSP90) leads to STAT3 dephosphorylation, cell growth inhibition and lymphoma control in a Patient Derived Tumor Xenografted (PDTX) model." (PMID 26501073, 2015). "We also analyzed known lymphoma oncogenes - NFkB and STAT3 - to find out if their expression could be regulated by these oncogenes." (PMID 26521025, 2015). "Caution should be taken when targeting STAT3 in lymphoma as it may provoke adverse effects on immune surveillance in these patients." (PMID 24473086, 2014). "The study of the underlying pathological context, the cytogenetical and TCR-γ clonality analyses and the search of mutations in the SH2 domain of STAT3 and STAT5b should help to distinguish LGL leukemia or other malignant lymphomas from non clonal CD8+ T-cell expansions." (PMID 24618699, 2014). "In addition, it appears that the anti-lymphoma effects of IL-21 are dependent on a mechanism involving the IL-21-activated STAT3 upregulation of c-Myc, in which c-Myc is a highly prognostic marker in DLBCL." (PMID 24959288, 2014). "Furthermore, rituximab has also been suggested to induce apoptosis of lymphoma cells by the inhibition of STAT3 phosphorylation." (PMID 24624997, 2014). "Signalling through the IL9, IL21, and IL22 receptors has been shown to promote STAT3 activation in this lymphoma, and much of this may be due to autocrine signalling." (PMID 22852078, 2012). "Furthermore, AKT, NF-κB and STAT3 signaling are required for the growth of lymphomas driven by the expression of Epstein-Barr Virus latent membrane protein 1 (EBV-LMP1), and also for the survival of chronic lymphocytic leukemia (CLL) B cells." (PMID 20433747, 2010). "In addition, we observed that down stream K-Ras effector, Stat3, was down-regulated upon oncogene inactivation in lung tumors and lymphomas that regressed." (PMID 18461184, 2008). "Also, downregulation of Stat3 stopped lymphoma cell activation by C5a." (PMID 41030738, 2025). "Consequently, abnormal STAT3 expression promotes malignant transformation and tumor progression through oncogenic gene expression that have been observed in numerous human cancers, and lymphoma is one of them." (PMID 38817669, 2024). "Indeed, STAT3 was further activated by IL-6 after being treated with 15 min in A20 lymphoma." (PMID 37686472, 2023). "However, STAT3 PROTACs may have some limitations in targeting leukemia than lymphoma, because SD-36 demonstrates potent activity in five of nine lymphoma cell lines, while showing activity in only one of nine AML cell lines." (PMID 32718354, 2020). "The primary lymphoma cells used here express high levels of the IL‐6R α‐chain and of the signaling chain gp130 and are positive for the phosphorylated form of the signal transducer and activator of transcription STAT3, which mediates signal transduction downstream of the IL‐6R heterodimer." (PMID 31515941, 2019). "Therefore, STAT3 is a promising therapeutic target in lymphoma." (PMID 31861597, 2019). "In addition, STAT3-targeted RNAi therapies, such as AZD9150 (16-oligonucleotide antisense molecule targeting the 3′ untranslated part of STAT3), also exhibited single-agent antitumor activity in patients with lymphoma or NSCLC in a phase I dose escalation study." (PMID 31619200, 2019).
lymphoma (continued). "Together, EATL appears driven by STAT3-mediated inflammation and immune evasion, while MEITL is a cytotoxic lymphoma with high expression of innate-like T/NK-cell genes (e.g., STAT4, NCAM1) and an “immune-cold” profile with low inflammation." (PMID 41057685, 2026). "In summary, our results demonstrate that STAT3, MYC, and EBNA1 collaborate to regulate the expression of ZC3H18, a protein that is upregulated in EBV+ lymphomas." (PMID 40354417, 2025). "al. also noted the increased expression of STAT3, GZMB and TNFRSF8 (CD30) as important markers of the HIV+ lymphomas." (PMID 40627772, 2025). "Compared with WT group and KO group, KO + lymphoma cell group and WT + lymphoma cell group had significantly increased expression levels of STAT3 and STAT6, indicating that lymphoma cells can activate STAT3 and STAT6." (PMID 38261741, 2024). "As this lymphoma is highly dependent on the constitutive activation of STAT3, 5-AZA impaired PEL cell survival, and when used in combination with AG490 JAK2/STAT3 inhibitor, it potentiated its cytotoxic effect." (PMID 38534772, 2024). "In this study, we explored the possibility of using a demethylating agent to target STAT3 in PEL cells for the first time, as inhibition of STAT3 represents one of the few promising opportunities to treat this aggressive lymphoma." (PMID 38534772, 2024). "Together, these studies reveal the STAT3, and ATP and Itaconate metabolism as key regulators of MDSC metabolic fitness which determines the response to doxorubicin therapy in the EL4 lymphoma model." (PMID 38555305, 2024). "Our group previously developed a highly potent STAT3 PROTAC degrader with excellent tumor inhibitory effects in leukemia and lymphoma cell lines, supporting the notion that PROTAC degraders have the potential to be developed for clinical use67." (PMID 38586029, 2024). "To confirm the importance of the STAT3-pathway, ATP and itaconate metabolism in the control of MDSC fitness and lymphoma treatment outcomes, we targeted the pathway in the EL4 (i.v.)lymphoma model." (PMID 38555305, 2024). "Several pro-survival and oncogenic pathways, such as, for example, STAT3 and PI3K/AKT/mTOR, can be activated by KSHV proteins, making this lymphoma particularly aggressive and difficult to treat." (PMID 39339966, 2024). "The expression levels of p-STAT3 and p-STAT6 in KO + lymphoma cell group were significantly inhibited compared with WT + lymphoma cell group, and their levels only slightly increased compared with WT group and KO group." (PMID 38261741, 2024). "In KO + lymphoma cell + IXA4 group, the expressions of activated STAT3 and STAT6 were similar to that in WT + lymphoma group, while the expressions of p-STAT3 and p-STAT6 were significantly higher than those in KO + lymphoma cell group." (PMID 38261741, 2024). "A positive feedback loop involving HSPs and STAT3 assumes a pivotal role in sustaining DNA Damage Response (DDR) and preventing DNA damage in Primary Effusion Lymphoma (PEL) cells." (PMID 38336777, 2024). "Research conducted by Hong and colleagues using the lymphoma model was based on the application of AZD9150, a next-generation antisense oligonucleotide inhibitor of STAT3." (PMID 38067351, 2023). "It decreased the STAT3 expression in B cell lymphoma cell lines (A20, SU-DHL-2 and OCI-Ly3), resulting in reduced proliferation of lymphoma cells featured with lower S-phase and higher apoptosis." (PMID 37686472, 2023).